STAT3 (signal transducer and activator of transcription 3)
Diseases named in the same sentence as STAT3 in open-access papers (continued):
Sharing a sentence is not in itself a finding about the gene and the disease.
lung carcinoma (continued). "Through the IL-6/STAT3 signalling pathway, CAFs enhance the metastatic potential of lung cancer cells, promoting angiogenesis by elevating VEGF and bFGF levels, facilitating cancer invasion and migration." (PMID 40407951, 2025). "N-terminal glycine myristoylation confers hydrophobicity to EZH2, which drives LLPS of EZH2 in lung cancer cells, compartmentalizes the substrate STAT3, and activates STAT3 signaling, ultimately facilitating rapid lung cancer cell proliferation." (PMID 40642070, 2025). "Hyperactivation of STAT3 is found in many types of cancers, including breast, cervical, colon, pancreatic, ovarian, and lung cancers, as well as cancers of hematologic origin." (PMID 41380973, 2025). "TGF-β promotes EMT and metastatic progression in lung cancer, while IL-6 activates signal transducer and activator of transcription 3 (STAT3) signaling to support tumor cell survival and proliferation." (PMID 41409273, 2025). "The Western blotting results revealed that, compared with the control group, the BMSC, QSFZYL, IFN-γ + BMSC + QSFZYL, and IFN-γ-BMSCs groups exhibited reduced PD-L1, JAK2, STAT3, and p-STAT3 expression in lung cancer tissues." (PMID 40642092, 2025). "Another study showed that CUR can reduce tumors by blocking the JAK2/STAT3 signaling pathway, indicating its potential for lung cancer treatment." (PMID 40860906, 2025). "AKT1, EGFR, HSP90AA1, SRC, and STAT3 exhibited the highest degree values and were identified as core therapeutic targets for lung cancer." (PMID 41465428, 2025). "For instance, in colon and lung cancer cell lines, STAT3 is upregulated by iron-dependent activation of cyclin-dependent kinase 1, and it promotes the expression of GPX4, a key regulator of ferroptosis resistance." (PMID 40867343, 2025). "In NCI-H889 lung cancer cells, derived from a metastatic site, Filgotinib effectively inhibited STAT3 activation, underscoring its potential in targeting the TME." (PMID 40407951, 2025). "While preclinical studies provide strong evidence for the inhibitory effects of CUR and RES on STAT3 signaling and lung cancer progression, there is an urgent need for well‐designed clinical trials." (PMID 40860906, 2025). "Both STAT3 and miRNA-21 play roles in regulating tumor cell migration in lung cancer brain metastasis." (PMID 41416095, 2025). "A specific flavonoid glycoside modulates integrin β1, EGFR, COX-2, MMPs, EMT markers, and STAT3/NF-κB/PI3K pathways in lung cancer." (PMID 41346617, 2025). "This comprehensive review has elucidated the therapeutic potential of CUR and RES as dual modulators of the STAT3 pathway in lung cancer." (PMID 40860906, 2025). "Collectively, these findings suggest that AKT1, EGFR, HSP90AA1, SRC, and STAT3 represent important therapeutic targets for anti-lung cancer intervention." (PMID 41465428, 2025). "Mechanistically, oncrasin-72 promotes apoptosis in lung cancer via ROS generation following STAT3 inhibition." (PMID 40867324, 2025). "CUR inhibits STAT3 activation, leading to reduced tumor growth, angiogenesis, and metastasis in nonsmall cell lung cancer (NSCLC) models." (PMID 40860906, 2025). "The combination of Vincristine and Crizotinib inhibits tumor cell proliferation and blocks the RAS/MAPK, PI3K/AKT, and JAK/STAT3 signaling pathways in nonsmall cell lung cancer EML4-ALK V1 cells." (PMID 40662801, 2025). "This study, utilizing public databases, demonstrated that elevated expression of STAT3 and ACC1 in lung cancer patients is associated with higher risk and poorer prognosis." (PMID 38495496, 2024). "On the other hand, inhibition of STAT3 abrogates erlotinib resistance in lung cancer cells, suggesting a feedback loop between STAT3 and EGFR." (PMID 39967270, 2024).
lung carcinoma (continued). "Specific EV-microRNAs within the exosomes, including miR-193a-3p, miR-210-3p, and miR-5100, were implicated in promoting EMT and the invasion and metastasis of lung cancer cells by activating the STAT3 signaling pathway." (PMID 39273095, 2024). "High expression of O-glycans has been observed in lung cancer patients and are a consequence of signal transducer and activator of transcription 3 (STAT3) hyper-activation induced by the PI3K/Akt pathway, which has been implicated in oncogenesis." (PMID 39123480, 2024). "To investigate the effect of RT right-half analogs on STAT3 in lung cancer cells, we synthesized new right-half derivatives of RT, modifying the C- and E-ring parts based on SAR." (PMID 39195486, 2024). "The JAK/STAT3 pathway is known to promote lung cancer progression, with overexpression of p‐STAT3 correlating with poor prognosis." (PMID 39099000, 2024). "LPS by itself is capable of accelerating lung cancer growth in vivo, partially through macrophage infiltration and activation of NF-κB and STAT3 signaling, providing an additional route for smoking-induced oncogenesis." (PMID 38570533, 2024). "We found that RPTOR promoted the cerebral invasion of the NSCLC lung cancer cells by the SPHK2/S1P/STAT3 axis." (PMID 38163890, 2024). "Research on breast and lung cancer cells has shown that MH can inhibit the activity of the cancer-promoting transcription factor p-STAT3." (PMID 39101096, 2024). "One particular study revealed that curcumol showed inhibitory effects on STAT3 phosphorylation in several cell lines, including A549 lung cancer cells, HeLa cervical cancer cells, and Hep3B liver cancer cells, thus effectively inhibiting tumor progression." (PMID 39690423, 2024). "A significant body of evidence points to the importance of upstream regulators of STAT3 in lung cancer development, for example, EGFR and Src,34 our study highlights JAK1 as a candidate kinase for STAT3 phosphorylation and activation in LUSC." (PMID 39099000, 2024). "Research has shown that regulating the STAT3/PD-L1 pathway can effectively increase apoptosis in lung cancer cells." (PMID 38441416, 2024). "We propose a regimen of dual inhibition of HOXC10 and STAT3 for improving the effectiveness of HOXC10 inhibition alone in KRAS-mutant lung cancer bone metastasis." (PMID 39191757, 2024). "In several types of cancer, including lung cancer, STAT3 is constitutively active, leading to continued expression of target genes that promote cell proliferation, survival, and invasion." (PMID 38388902, 2024). "Zerumbone is a naturally occurring compound derived from ginger rhizome, which can be used in combination with thyrosine kinase inhibitors like gefitinib for treatment of lung cancer, acting by inducing ferroptosis and inhibiting Akt/STAT3/SLC7A11 axis." (PMID 39104501, 2024). "Despite these limitations, the findings from our research offer significant insights for the clinical application of ITCH E3 ligase, miR494 or STAT3 as potential targets in the future exploration of lung cancer." (PMID 39099000, 2024). "Alantolactone, a sesquiterpene lactone component of Inula helenium, abrogates STAT3 activation by promoting STAT3 glutathionylation, leading to oxidative stress-dependent apoptosis in lung cancer." (PMID 38245798, 2024). "Strikingly, inhibition of HOXC10 in combination with STAT3 inhibitor was effective against KRAS-mutant lung cancer bone metastasis by triggering ferroptosis." (PMID 39191757, 2024). "It has been reported that the M2 TAM polarization was affected by RSV due to a significant decrease in STAT3 activity, an effect observed both in lung cancer cells and in a mouse lung cancer model." (PMID 39220125, 2024). "The results indicated that lung cancer patients with higher STAT3 and ACC1 expression had significantly poorer overall survival (OS)." (PMID 38495496, 2024). "The MAPK, STAT3, and NF-κB signaling pathways are closely related to the pathogenesis of lung cancer." (PMID 39469948, 2024).
lung carcinoma (continued). "This study underscores the potential of enhancing stability and targeting of ChNPs to improve the efficacy of cancer cell lysis, for targeted delivery of STAT3-targeting siRNA to lung cancer cells." (PMID 39065565, 2024). "These NPs effectively delivered STAT3-targeting siRNA in lung cancer cells, exhibiting increased cellular uptake (75%) attributed to folic acid-mediated receptor binding and endocytosis." (PMID 39065565, 2024). "In lung cancer, IL-6 and IL-17 upregulate RORγt through STAT3 signaling mechanisms in order to produce IL-17 isoforms, IL-17A/F." (PMID 38279220, 2024). "A previous study has shown that the Akt and STAT3 signaling pathways are involved in the EMT process in lung cancer cells.." (PMID 38388902, 2024). "This suggests the importance of the MPC1/STAT3 axis in the progression of lung cancer and provides a new perspective for molecular targeting of the STAT3 pathway." (PMID 39179991, 2024). "This will help inform the combination use of FDA-approved MEK inhibitors and STAT3 inhibitor in an ongoing phase I clinical trials (ClinicalTrials.gov ID:NCT03195699) to treat with KRAS-mutant lung cancer bone metastasis patients." (PMID 39191757, 2024). "TANs have also been reported to secrete the cytokine IL-10 to facilitate the activation of c-Met/STAT3 signaling which promoted the distant metastasis of lung cancer cells." (PMID 38765006, 2024). "In this study, we found that IL6/STAT3 pathway confers resistance to HOXC10 inhibition in KRAS-mutant lung cancer bone metastasis and that activation of p-STAT3Tyr705 further promotes cell survival after HOXC10 inhibition." (PMID 39191757, 2024). "Activation of LPAR1 induces Janus kinase 2 (JAK2) and signal transducer and activator of transcription 3 (STAT3) signalling to promote lung cancer cell migration." (PMID 38607068, 2024). "We have previously shown that SKI and SnoN oncoproteins cooperate with phosphorylated STAT3 in an adenocarcinoma lung cancer cell line, HCC827, to repress transcription of the Smad3 gene, which renders the sensitive cells resistant to gefitinib." (PMID 38960622, 2024). "LDOC1 interacts with Ligand-of-Numb protein X1 (LNX1), an E3 ligase, to induce Janus kinase 2 (JAK2) ubiquitination and degradation, which negatively regulates STAT3 activation and IL-6 secretion in lung cancer cells." (PMID 39682774, 2024). "Hypoxic bone marrow-derived mesenchymal stem cells derived exosome mediates transfer of several miRNAs that promote metastasis of lung cancer cells via STAT3-induced EMT." (PMID 38245798, 2024). "Research shows that the dysregulation of the IL-6/STAT3 signaling pathway mediates lung cancer cell proliferation and invasion, and the suppression of the IL-6/STAT3 pathway prevents the progression of lung cancer." (PMID 39258670, 2024). "Further research has found that cigarette smoke can induce EMT in lung cancer by activating signaling pathways such as STAT3, AKT, and NF-kB." (PMID 39472448, 2024). "Previous studies have shown that, CAFs in the TME can secrete IL-6, which stimulates STAT3 signaling in lung cancer cells and promotes metastasis." (PMID 38424624, 2024). "In non-small cell lung cancer, in vitro experiments demonstrate that CXCL12 binding to CXCR4, via activation of the JAK2/STAT3 signaling pathway, reduces the proportion of lung cancer cell apoptosis induced by the chemotherapeutic drug cisplatin." (PMID 38920657, 2024). "Persistent activation of STAT3 and NF-κB has been shown to be important mechanisms of tumorigenesis in lung cancer." (PMID 39469948, 2024). "Metastasis cancer studies, including those of lung cancer, have demonstrated that STAT3 is essential for maintaining Slug, Snail, and Vimentin expression." (PMID 39195486, 2024). "Using dual luciferase activity, researchers discovered that miR-526b-3p detrimentally controls the amount of STAT3 in lung cancer cells." (PMID 39343796, 2024).
lung carcinoma (continued). "STAT3 is constitutively activated in many cancer types, including lung cancer, and can induce cancer cell proliferation and cancer stem cell (CSC) maintenance." (PMID 38760429, 2024). "Intriguingly, inhibition of HOXC10 plus STAT3 inhibitor in combination was effective against KRAS-mutant lung cancer bone metastasis by triggering ferroptosis." (PMID 39191757, 2024). "For example, afatinib-induced STAT3 activation decreases the suppression of lung cancer cells to afatinib, and inhibiting IL-6R/JAK1/STAT3 signaling reverses the resistance." (PMID 36902166, 2023). "Myristoylation of EZH2 also augments its interaction with STAT3, thereby enhancing STAT3 Y705 phosphorylation and transcriptional activity, which ultimately propels lung cancer progression." (PMID 38034101, 2023). "Interleukine-17 is a proinflammatory cytokine that promotes lung cancer growth and progression though the activation of the STAT3, NF-κB, and AP-1 signaling pathways." (PMID 37894738, 2023). "Based on low toxicity, high integration into A549 lung cancer cells, and the silencing of STAT3 expression as observed in vitro, they selected VCH particles for further research in cancer therapy." (PMID 38067351, 2023). "The number of surviving SK-MES-1 and A549 lung cancer cells treated with STAT3 shRNA and irradiation was lower than the untreated control cells." (PMID 38067351, 2023). "As expected, DGG-100629-induced lung cancer cell death was reversed by overexpressing DDIAS or STAT3." (PMID 37121974, 2023). "CircAKT3 and STAT3 were highly expressed in human lung cancer, and miR-516b-5p were simultaneously downregulated." (PMID 37599427, 2023). "TGF-beta stimulates STAT3 expression and induces epithelial-mesenchymal transition in lung cancer cells through activation of STAT3 signaling pathway." (PMID 37228122, 2023). "Recent scholarly contributions have revealed that ZDHHC19 (Z19) functions as a palmitoyl acyltransferase that modulates STAT3 in lung cancer." (PMID 38034101, 2023). "Icotinib resistance resulted from the increased expression of autophagic flux (ATG3, ATG5, and ATG7) via STAT3-FOXM signaling in lung cancer cells." (PMID 36834846, 2023). "The intraperitoneal injection of NsiRNA resulted in a significant STAT3 mRNA and protein reduction in the tumor samples in opposition to naked STAT3 siRNA treatment, as indicated in a xenograft lung cancer model." (PMID 38067351, 2023). "We further showed that overexpression of exogenous STAT3 reversed the decrease in EME1 expression in FIBP-deficient lung cancer cells, indicating that FIBP upregulates EME1 in a STAT3-dependent manner." (PMID 37564211, 2023). "For example, loss of STAT3 expression was found to synergize with driver mutations to promote brain or melanoma metastasis, whereas in lung cancer and PCa mouse models, disruption of STAT3 suppressed lung or prostate cancers compared to the wild-type cohort." (PMID 37573301, 2023). "Due to the key roles of the STAT3 pathway, it is considered as a promising therapeutic target for lung cancer treatments." (PMID 38137415, 2023). "It is upregulated in lung cancer and stimulates malignant phenotypes of lung cancer cells by upregulating STAT3." (PMID 37656243, 2023). "Apparently, DDIAS activates STAT3 and promotes migration and invasion by expressing genes such as survivin, slug, and vimentin in response to interleukin-6 (IL-6) in lung cancer cells." (PMID 37121974, 2023). "We confirmed that these cell-biological effects are applicable to lung carcinoma, as overexpressing RalA in H2170 lung carcinoma cells increased Src and Stat3 phosphorylation." (PMID 36632230, 2023). "Further, we have shown that MUC16 promotes lung cancer migration via STAT3/glucocorticoid receptor (GR)/testis-specific protein Y-encoded-like 5 (TSPYL5) axis." (PMID 36918912, 2023). "While OGT-mediated O-GlcNAcylation promoted STAT3 phosphorylation and transcriptional activity in lung cancer." (PMID 38008713, 2023).
lung carcinoma (continued). "DDIAS competes with PTPRM to bind to STAT3, allowing STAT3 Y705 phosphorylation to persist in lung cancer." (PMID 37121974, 2023). "The inhibition of STAT3, which was previously well documented in the chemoprevention of lung cancer, was investigated in more detail through hybridization of curcumin with a synthetic moiety to increase the ROS level." (PMID 37376060, 2023). "Blocking STAT3 was reported to be a new potential therapeutic strategy for gefitinib resistance in lung cancer." (PMID 36525508, 2023). "The remodeling of endothelial cells and the upregulation of cell adhesion molecules by melanoma and lung carcinoma cells was found to be mediated via hijacking the endothelial signal transducer activator of transcription 3 (STAT3)." (PMID 37373202, 2023). "Niko P. Bretz scrutinised CD24 expression in A549 lung cancer, SKOV3ip ovarian cancer, and HS683 and SNB19 glioblastoma cells, and discovered that Src, activated by CD24 tyrosine, phosphorylates STAT3 signalling molecules, which causes the activation of STAT3." (PMID 38137380, 2023). "Our research indicated that β‐elemene suppressed proliferation and enhanced sensitivity to gefitinib by inducing apoptosis through the FBP1/STAT3 axis in gefitinib‐resistant lung cancer cells." (PMID 36525508, 2023). "It is known that the activation of this pathway leads to an upregulation of various genes that are implicated in cell survival and proliferation, and we show here that PA stimulates lung cancer cell migration through the JAK2/STAT3 pathway." (PMID 37509443, 2023). "In summary, our study identified the miR-182/IL-8/STAT3 axis as an important signaling pathway in regulating osteolytic metastasis of lung cancer." (PMID 37127752, 2023). "Ovarian cancer EV miR-630 has been found to activate NF-κB and lung cancer EV miR-210 activated the janus kinase 2/signal transducer and activator of transcription 3 (JAK2/STAT3) pathway, prompting the switch of fibroblasts to CAFs." (PMID 37978566, 2023). "PPI also promoted gastric cancer cell apoptosis by suppressing STAT3 signaling, while helping lung cancer cells overcome their resistance to erlotinib treatment via inhibition of STAT3." (PMID 38027010, 2023). "The in vitro research using STAT3 shRNA transfected into H1650 lung cancer cells showed that construct decreased STAT3 on the mRNA and protein levels." (PMID 38067351, 2023). "18β-Glycyrrhetinic acid can induce apoptosis and G2/M cell cycle arrest and inhibit migration via ROS/MAPK/STAT3/NF-κB signaling pathways in A549 lung cancer cells." (PMID 36654811, 2023). "Since our finding demonstrated that STAT3 exhibited the most potential target of compounds in lung cancer cells, molecular dynamic simulation between STAT3 and AA or AB was then performed." (PMID 36707691, 2023). "Recent studies have shown that the overexpression of HPV-16 E6 and E7 oncoproteins enhanced epithelial-mesenchymal transition (EMT) by activating STAT3 signaling pathway to promote bone metastasis in lung cancer." (PMID 36755257, 2023). "Silencing STAT3 by shRNA in lung cancer cell lines A549 and SPC-A1 suppressed STAT3 on mRNA and protein levels." (PMID 38067351, 2023). "In fact, STAT3 interaction with ATXN3 was detected in transiently transfected HEK293T cells as well as endogenously in human lung cancer A549 cells." (PMID 38038129, 2023). "In vitro study indicated that lung cancer cells treated with STAT3 shRNA and cisplatin had decreased cell viability and the ability for colony formation." (PMID 38067351, 2023). "The results showed that rhTβ4 inhibited the phosphorylation of JAK2/STAT3 proteins in lung cancer cells (A549) and lung fibroblasts (Mlg)." (PMID 36835236, 2023).